BRPF1 (bromodomain and PHD finger containing 1)
Description:
Scaffold subunit of various histone acetyltransferase (HAT) complexes, such as the MOZ/MORF and HBO1 complexes, which have a histone H3 acetyltransferase activity. Plays a key role in HBO1 complex by directing KAT7/HBO1 specificity towards histone H3 'Lys-14' acetylation (H3K14ac). Some HAT complexes preferentially mediate histone H3 'Lys-23' (H3K23ac) acetylation. Positively regulates the transcription of RUNX1 and RUNX2.
Synonyms: BR140; IDDDFP
Tractability: Small molecule: a structure with a bound ligand is known; a high-quality ligand is known. Antibody: its Gene Ontology location is reachable by antibodies, with high confidence. PROTAC: ubiquitination databases record sites on it; its protein half-life has been measured; a small molecule that binds it is known.
Target class: Epigenetic regulator; Bromodomain; Reader
Chemical probes: GSK-5959, GSK6853 (high quality), NI-42, NI-57 (high quality), OF-1 (high quality), PFI-4 (high quality), PMID25974391C34 (high quality)
Gene: Protein-coding gene on chromosome 3 (9,731,729 to 9,748,019, forward strand). Ensembl gene ENSG00000156983.
Subcellular location: Nucleus; Chromosome; Cytoplasm
Subcellular location (Human Protein Atlas): Nucleoplasm
Pathways (Reactome):
Chromatin organization: HATs acetylate histones
Gene Ontology:
Molecular function: acetyltransferase activator activity; histone H4K12 acetyltransferase activity; histone H4K5 acetyltransferase activity; histone H4K8 acetyltransferase activity; protein binding; histone reader activity
Biological process: chromatin remodeling; positive regulation of DNA-templated transcription; regulation of DNA-templated transcription; regulation of developmental process; regulation of hemopoiesis
Cellular component: chromosome; cytoplasm; histone acetyltransferase complex; MOZ/MORF histone acetyltransferase complex; nucleoplasm; nucleus
Genetic constraint (gnomAD): Loss-of-function variants: 15 observed, 112.41 expected, observed/expected ratio (o/e) 0.13, 90% interval 0.088 to 0.2. The upper end of that interval is the gene's LOEUF score, 0.2, which puts it in group 1 of 6, group 1 being the genes least tolerant of losing a copy. Missense variants: 1,115 observed, 1,675.5 expected, observed/expected ratio (o/e) 0.67, 90% interval 0.63 to 0.7. Synonymous variants: 646 observed, 638.29 expected, observed/expected ratio (o/e) 1.01, 90% interval 0.95 to 1.08.
Gene-disease validity (ClinGen):
ClinGen rates the evidence that BRPF1 causes each of these diseases.
syndromic complex neurodevelopmental disorder (autosomal dominant): Definitive. A disorder that involves more than one phenotype associated with the central nervous system, including but not limited to intellectual disability, autism, and seizures (epilepsy), and also a distinctive pattern of other features including dysmorphisms and/or congenital malformations.
Homologues: Orthologues: chimpanzee BRPF1 (99% identical), macaque BRPF1 (99% identical), dog BRPF1 (99% identical), pig BRPF1 (99% identical), mouse Brpf1 (98% identical), rat Brpf1 (98% identical), guinea pig BRPF1 (97% identical), rabbit BRPF1 (97% identical), tropical clawed frog brpf1 (85% identical), zebrafish brpf1 (64% identical), Drosophila melanogaster Br140 (41% identical), Caenorhabditis elegans lin-49 (19% identical), and 1 more. Paralogues in human: BRPF3 (49% identical), BRD1 (49% identical), JADE3 (16% identical), JADE1 (16% identical), JADE2 (15% identical), MLLT10 (15% identical), MLLT6 (14% identical), PHF14 (14% identical).
Diseases named in the same sentence as BRPF1 in open-access papers:
BRPF1 is named in the same sentence as 43 diseases in open-access papers, as found by Europe PMC text mining. Sharing a sentence is not in itself a finding about the gene and the disease. The quoted sentences say what the papers report.
Intellectual disability (16 papers, 2019 to 2025). "For most of the genetic conditions, the presence of intellectual disability was confirmed or parent‐reported, except for individuals with the BRPF1 or FOXP2 variants." (PMID 39846212, 2025). "The mutations of the BRPF1 gene in humans are also related to neurodevelopmental disorders with syndromic intellectual disability." (PMID 36768434, 2023). "The variant was deemed to be pathogenic because of the association of variants in BRPF1 with intellectual disability." (PMID 37316925, 2023). "BRPF1, encoding a histone acetyl transferase, has also been associated with intellectual disability and dysmorphic features." (PMID 36117209, 2023). "Disruptions of BRPF1 are associated with a specific form of intellectual disability consistent with the proband’s phenotype (OMIM: 617333)." (PMID 37316925, 2023). "Those patients with BRPF1 mutations often display intellectual disability or suffer from leukemia or medulloblastoma." (PMID 36077605, 2022). "Patients with monoallelic bromodomain and PHD finger-containing protein 1 (BRPF1) mutations showed intellectual disability." (PMID 34485298, 2021). "Accumulating clinical studies have reported totally 40 cases of patients with BRPF1 monoallelic mutations, with symptoms such as intellectual disability, developmental delay, and epilepsy." (PMID 34485298, 2021). "Recently, another study showed that novel de novo nonsense mutation in BRPF1 gene leads to intellectual disability, coloboma, facial nerve palsy, and hypoplasia of the corpus callosum." (PMID 32457794, 2020). "Consistent with the recent description of the BRPF1‐associated phenotype, the affected individuals showed developmental delay and mild to moderate intellectual disability." (PMID 31020800, 2019). "To conclude, BRPF1 haploinsufficiency is an underdiagnosed cause of intellectual disability of variable severity, ptosis and/or blepharophimosis and additional nonspecific features, and should be considered in relevant clinical circumstances." (PMID 31020800, 2019). "We describe herein four additional affected individuals of a single family, exhibiting intellectual disability of variable severity and distinct facial features, found to harbor a novel mutation in BRPF1." (PMID 31020800, 2019). "Additionally, defective mutations of BRPF1 lead to intellectual disability and facial dysmorphisms in humans." (PMID 36357379, 2022). "Although recent studies have suggested that SETD5 and SRGPA3 are the key genes involved in intellectual disability in 3p deletion syndrome, the genetic test results in the present case showed that BRPF1 deletion may also cause intellectual disability." (PMID 33643973, 2021). "Bromodomain and PHD finger-containing protein 1 (BRPF1) is an important candidate gene with its monoallelic mutations resulting in intellectual disability, but the exact underlying mechanism remains unclear." (PMID 34485298, 2021). "Furthermore, some of the cases with the mutation in BRPF1 gene also leads to cause variable degrees of intellectual disability, distinct facial features including downslanted palpebral fissures, ptosis, and/or blepharophimosis." (PMID 32457794, 2020). "Recently, variants in BRPF1, encoding a chromatin reader, have been associated with a previously unrecognized autosomal dominant syndrome manifesting with intellectual disability (ID), hypotonia, dysmorphic facial features, ptosis, and/or blepharophimosis in 22 individuals." (PMID 31020800, 2019). "Bromodomain and PHD finger containing 1 (BRPF1)-related neurodevelopmental disorder is characterized by intellectual disability, developmental delay, hypotonia, dysmorphic facial features, ptosis, and blepharophimosis." (PMID 37946714, 2023). "For example, breakpoints of a 12 kb copy neutral inversion identified in monozygotic twins suffering from intellectual disability disrupt genic regions of BRPF1 and CPNE9." (PMID 35484572, 2022).
Intellectual disability (continued). "In this case, the child had intellectual disability, and the genetic test results suggested the deletion of BRPF1 gene." (PMID 33643973, 2021). "One such chromatin reader now linked to a recognizable intellectual disability phenotype, is Bromodomain and PHD finger‐containing protein 1 (BRPF1; OMIM *602410)." (PMID 31020800, 2019). "Heterozygous variants in BRPF1 are associated with intellectual developmental disorder with dysmorphic facies and ptosis (IDDDFP), characterized by delayed psychomotor and language development, intellectual disability, and dysmorphic features." (PMID 33418956, 2021). "Besides BRPF1, related histone acetyltransferases MOZ and MORF were also found mutated in patients with abnormal neurodevelopment and intellectual disability; however, no studies of their effect on the electrophysiology of neurons have been reported." (PMID 34485298, 2021). "Recently, Brpf1 was reported as a candidate gene for intellectual disability (ID)." (PMID 31213987, 2019). "BRPF1 deletion may lead to intellectual disability and abnormal facial features, such as ptosis." (PMID 33643973, 2021). "The lack of BRPF1 can also lead to multiple gene (such as Robo3 and Otx1) transcription reduction, the loss of neuronal migration and neural tube closure, the control of transcriptional regulation, and it can cause neurodevelopmental disorders, which can result in intellectual disability." (PMID 33643973, 2021). "Among genes with predicted probabilities greater than 0.90 (ranks 1–55), four genes (WDR45, CLTC, BRPF1, and GATAD2B) do not possess SFARI annotations, but have been associated with neurodegeneration and intellectual disability according to OMIM annotations." (PMID 35596027, 2023). "In the present case, the heterozygous deletion of BRPF1 appeared to have led to intellectual disability and ptosis, but not to hearing abnormalities or renal and gastrointestinal malformations." (PMID 33643973, 2021).
ptosis (8 papers, 2019 to 2023). The drooping of the upper eyelid. "Deleterious variants in BRPF1 are associated with Intellectual developmental disorder with dysmorphic facies and ptosis (OMIM:617333)." (PMID 35484572, 2022). "Mutations in BRPF1 have also been shown to cause intellectual developmental disorder with dysmorphic facies and ptosis (MIM: 617333), an autosomal dominant condition." (PMID 32457794, 2020). "Here, we report a Saudi family with novel missense variant in heterozygous state in the BRPF1 gene leading to the intellectual developmental disorder with dysmorphic facies and ptosis." (PMID 32457794, 2020). "A study of 10 patients (of which nine came from unrelated families) with intellectual developmental disorder, dysmorphic faces, and ptosis found these were due to heterozygous mutations in the BRPF1 gene." (PMID 32457794, 2020). "We consider such cases to be BRPF1 ptosis, resulting from gene deletion." (PMID 33643973, 2021). "In addition, the BRPF1 gene plays a role in craniofacial development, and it has also been confirmed that a lack of BRPF1 can cause ptosis and (or) narrow palpebral fissure." (PMID 33643973, 2021).
medulloblastoma (7 papers, 2020 to 2024). A malignant, invasive embryonal neoplasm arising from the cerebellum. "BRPF1 has been implicated as tumor suppressor in childhood leukemia, prostate cancer and medulloblastoma." (PMID 36712963, 2022). "Moreover, somatic BRPF1 mutations have been identified in sonic hedgehog medulloblastoma and pediatric cancers." (PMID 38346967, 2024). "In addition to germline mutations in patients with neurodevelopmental disorders, somatic mutations of BRPF1 have been reported in leukemia, medulloblastoma and other types of cancer." (PMID 36077605, 2022). "Since the BRPF1 expression levels are significantly lower in medulloblastoma when compared to normal tissue, it supports a tumor suppressor function." (PMID 36712963, 2022). "Truncated BRPF1 protein, cooperating with SmoM2 activation, promotes postmitotic neuron dedifferentiation, re-entering the cell cycle and inducing medulloblastoma in vivo." (PMID 36077605, 2022). "Recently, truncated BRPF1, which is found in human medulloblastoma patients, was shown to promote the medulloblastoma formation with SmoM2 from postmitotic neurons in adult mice." (PMID 36712963, 2022). "BRPF1 is a core subunit of the histone acetyltransferase complex that acts as a tumor suppressor in childhood leukemia and adult medulloblastoma and an oncogene in acute myeloid leukemia (AML)." (PMID 32098402, 2020). "We anticipate that future experiments with the non-histone interacting partners identified in this study will be immensely helpful to gain a detailed understanding of BRPF1 in transcriptional regulation, brain development, adult medulloblastoma, and leukemogenesis." (PMID 38072045, 2023). "Moreover, the BRPF1 expression is lower in medulloblastoma, while in our study, BRPF1 expression is upregulated in several cancer types." (PMID 34285329, 2021). "Furthermore, truncated BRPF1 was found in SHH subtype medulloblastoma (SHH-MB) in adult humans and induced SHH-MB upon SmoM2 activation in adult mice." (PMID 34926268, 2021).
developmental delay (5 papers, 2019 to 2023). "The cumulative number of patients with BRPF1 mutations has reached 40, and patients were often accompanied with symptoms such as epilepsy, hypotonia, developmental delay, language dysfunction, ptosis, and cerebellar and facial deformities." (PMID 34485298, 2021). "Patients carrying heterozygous mutations of BRPF1 suffer from a neurodevelopmental disorder characterized by congenital hypotonia, facial dysmorphisms, global developmental delay, and ID, which suggests that Brpf1 may regulate brain development in a dosage-dependent manner." (PMID 31213987, 2019).
hepatocellular carcinoma (5 papers, 2021 to 2023). A malignant tumor that arises from hepatocytes. "Lastly, we used publicly available ChIP-seq and RNA-seq datasets to understand the colocalization of BRPF1 and interleukin enhancer–binding factor 3 in regulating gene expression in the context of hepatocellular carcinoma." (PMID 38072045, 2023). "In contrast, BRPF1 is frequently overexpressed in hepatocellular carcinoma (HCC)." (PMID 36712963, 2022). "Like other bromodomain-containing proteins, BRPF1 too is involved in various cellular processes like skeletal development, vertebrate segmentation and patterning, brain development and even in cancer-like hepatocellular carcinoma (HCC)." (PMID 38072045, 2023). "High BRPF1 contributes to tumor growth and malignant progression of PRAD, which is in accordance with findings in other solid tumors, like hepatocellular carcinoma (HCC)." (PMID 36357379, 2022).
leukemia (5 papers, 2015 to 2022). A malignant (clonal) hematologic disorder, involving hematopoietic stem cells and characterized by the presence of primitive or atypical myeloid or lymphoid cells in the bone marrow and the blood. "Related to human disease, BRPF1/KAT6A/KAT6B mutations have all been identified as the cause of neurodevelopmental disorders, leukemia and other types of cancer." (PMID 36077605, 2022). "As HATs activity is dysregulated in cancer and causes overexpression of oncogenes in different tumours, especially leukaemia, BRPF1 has been exploited as a biological target for the development of potent and selective BRPF and BRPF1 inhibitors." (PMID 36077415, 2022). "This screen reveals synthetic sick interactions between Brd9&Jmjd6, Kat6a&Jmjd6, and Brpf1&Jmjd6 in leukemia cells." (PMID 32661245, 2020). "MOZ–TIF2 forms a stable complex with bromodomain-PHD finger protein 1 (BRPF1), and MOZ–TIF2/BRPF1 associate with Hox genes in the MOZ–TIF2 driven leukemia cells." (PMID 26075180, 2015).
prostate carcinoma (5 papers, 2022 to 2025). A carcinoma that arises from epithelial cells of the prostate gland. "Further analysis of the specific cancer types revealed higher BRPF1 expression in lymphoma, while lower expression levels were observed in hepatobiliary, pancreatic, and prostate cancers." (PMID 38346967, 2024). "Our data collectively suggested the possible therapeutic implications of targeting USP35/BRPF1 as an innovative strategy to improve the overall prognosis in prostate cancer patients." (PMID 36357379, 2022). "BRPF1 in urine is considered a potential marker of prostate cancer." (PMID 36276071, 2022). "The MTT assay showed that BRPF1 knockdown remarkably inhibited prostate cancer cell growth." (PMID 36357379, 2022). "Similarly, in an independent study, we demonstrated that castration-resistant prostate cancer cells also depend on BRPF1 in docetaxel and cabazitaxel resistance, highlighting BRPF1’s role as an ABCB1 regulator controlling mTOR and unfolded protein response (UPR) signaling." (PMID 40583060, 2025). "In addition, USP35 can accelerate prostate cancer growth by deubiquitinating BRPF1." (PMID 37993419, 2023). "We reported that BRPF1 is a substrate of USP35 and USP35/BRPF1 axis promotes malignant features of prostate cancer via activating the MVA pathway." (PMID 36357379, 2022). "Last of all, we are still uncertain about the relationships between USP35/BRPF1/MVA axis and castration resistance in prostate cancer." (PMID 36357379, 2022).
breast carcinoma (4 papers, 2016 to 2025). "According to the cBioPortal for Cancer Genomics site, BRPF1 is found amplified in 27% of breast cancers or mutated in 9% of stomach cancers." (PMID 26626149, 2016). "Moreover, high BRPF1 expression was significantly associated with poorer survival in patients with breast cancer who received systemic chemotherapy." (PMID 40583060, 2025). "Analysis of publicly available breast cancer patient data also revealed elevated expression of BRPF1 in the basal subtype as well as in higher-grade tumors, indicating a role for BRPF1 in disease progression." (PMID 40583060, 2025). "In addition, BRPF1 expression positively correlated with increasing breast cancer grade, further distinguishing it from other complex members." (PMID 40583060, 2025). "Together, these findings indicate that BRPF1 may serve as both a prognostic marker and a potential contributor to chemotherapy resistance in patients with breast cancer." (PMID 40583060, 2025). "To understand the clinical significance of BRPF1 alongside the members of MOZ–MORF and HBO1 complexes, we analyzed publicly available breast cancer patient data from The Cancer Genome Atlas (TCGA), which includes all breast cancer subtypes, such as luminal A, luminal B, Her2 and basal subtype." (PMID 40583060, 2025). "Several BrD members, namely BRPF1, SMARCA4, BRD7, BRD9, BAZ1B, ATAD2 and BRD4 are significantly upregulated in basal breast cancer subtype (when compared to less aggressive luminal A and normal‐like subtype), which strongly mimics the results obtained for the mRNA‐SI." (PMID 35049055, 2022).
liver cancer (4 papers, 2021 to 2023). An epithelial or non-epithelial malignant neoplasm that arises from the liver. "Among the 22 common genes, epigenetic molecule BRPF1 contains bromodomain and has been identified as a therapeutic target for liver cancer." (PMID 34926268, 2021). "More importantly, BRPF1 contributed to liver cancer stemness by increasing the expression of stem cell factors and promoting self-renewal ability." (PMID 34285329, 2021). "Moreover, several studies have reported that abnormal BRPF1 expression plays an important role in many cancer types, including liver cancer, medulloblastoma, and leukemia." (PMID 36276071, 2022). "cDNA microarray analysis of PLC and Huh-7 cells revealed that BRPF1 expression was upregulated in CD133 + liver cancer stem cells when compared to its CD133- counterparts, indicating that BRPF1 may be associated with cancer stemness." (PMID 34285329, 2021). "In addition, SP1 was highly upregulated in liver cancer, and the expression of SP1 was positively correlated with BRPF1 expression." (PMID 34285329, 2021).